SP1 (Sp1 transcription factor)
Diseases named in the same sentence as SP1 in open-access papers (continued):
Sharing a sentence is not in itself a finding about the gene and the disease.
Alzheimer disease (18 papers, 2010 to 2025). A progressive, neurodegenerative disease characterized by loss of function and death of nerve cells in several areas of the brain leading to loss of cognitive function such as memory and language. "Sp1 is known to affect pathways associated with neuronal survival and death, and the dysregulation of SP1 has been associated with Alzheimer's disease." (PMID 20959017, 2010). "For example, the transcription factor Sp1 is involved in the transcriptional control of the human FE65 gene, which encodes an important adaptor protein that binds to the Alzheimer’s disease amyloid precursor protein." (PMID 36230922, 2022). "After systematic research, we believe that miR-590-3 and SP1 are key regulatory genes for Alzheimer's disease, which can promote neuronal apoptosis in patients with Alzheimer's disease through the AMPK signaling pathway." (PMID 34992508, 2021). "The GWAS analysis implicates that Sp1 mediates transcriptional activity changes in patients suffering from the neurodegenerative disorders, Alzheimer’s disease (AD) and Parkinson’s disease (PD)." (PMID 34830324, 2021). "SP1, a proinflammatory factor, is significantly elevated in the brain in patients with Alzheimer's disease or Parkinson's disease." (PMID 34970121, 2021). "This is interesting, since SP1 and ELK have been linked to memory function and Alzheimer's disease and are—amongst other kinases—activated via ERK1/2." (PMID 28768717, 2017). "A study has suggested that the elevation of SP1 levels could trigger cell death in neurodegenerative disorders, including Alzheimer’s disease, making it an interesting candidate for therapeutic intervention of neurodegenerative disorders." (PMID 31927536, 2020). "In addition, evidence has shown that SP1 was up-regulated in the progression of neurological diseases, such as Parkinson’s disease and Alzheimer’s disease." (PMID 31927536, 2020). "As previously reported, elevated expression of SP1 was found in Alzheimer’s disease brains." (PMID 31927536, 2020). "These targets were found to be related to metabolite interconversion enzymes, modified residues, regulation of apoptotic signaling pathway, “Alzheimer’s Disease, Focal Onset”, NFKB1, SP1, and RELA, hsa-miR-17-5p, hsa-miR-16-5p, and hsa-miR-26b-5p." (PMID 39493676, 2024). "“Acute Confusional Senile Dementia”, “Alzheimer’s Disease, Focal Onset”, NFKB1, SP1, and RELA were found to be the most important diseases and transcription factors." (PMID 39493676, 2024). "The role in inverse comorbidity of cancer and Parkinson’s disease/Alzheimer’s disease was shown for APOE, APOC1, SQSTM1, PSEN1, and SP1." (PMID 37298337, 2023). "Previous studies have demonstrated that Sp1 overexpression upregulates APP and BACE1 expression, which is involved in Alzheimer's disease." (PMID 31049134, 2019). "However, JUN, HDAC1, SP1, and STAT3 are also indispensable in the neuronal apoptosis mechanism of patients with Alzheimer's disease." (PMID 34992508, 2021).
nasopharyngeal carcinoma (18 papers, 2013 to 2025). A carcinoma arising from the nasopharyngeal epithelium. "Most notably, overexpression of SP1 was associated with tumor progression and reduced radiosensitivity in both nasopharyngeal cancer cell lines and tissue samples." (PMID 39800760, 2025). "As stated, it was upregulated in various malignant tumor cells associated with the malignant phenotype; for example, Sp1 was elevated in advanced nasopharyngeal carcinoma responsible for proliferation as well as clonogenicity." (PMID 29088790, 2017). "In summary, we investigated the expression level and potential role of Sp1 in nasopharyngeal carcinoma and its underlying mechanisms." (PMID 25099028, 2014). "The expression of specificity protein 1 (Sp1) and Sp3 is significantly increased in nasopharyngeal carcinoma cells." (PMID 40071086, 2025). "The knockdown of Sp1 induces G1 phase arrest and suppresses cell proliferation, clonogenicity and the expressions of stem cell markers in nasopharyngeal carcinoma." (PMID 37445835, 2023). "The circRNA originated from ZNF609 has been shown to adsorb miR-150-5p and to upregulate SP1 transcription factor, promoting the proliferation of nasopharyngeal carcinoma cells." (PMID 33432020, 2021). "Although Sp1 has been investigated extensively in multiple types of cancers, the level of Sp1 in nasopharyngeal carcinoma and molecular mechanisms by which Sp1 modulates the behavior of tumor cells remain elusive." (PMID 25099028, 2014). "In the present study, we revealed that higher level of Sp1 correlates with advanced tumor stage in nasopharyngeal carcinoma." (PMID 25099028, 2014). "Previous studies have revealed that hsa_circ_0000615 acts as miRNA sponge to exert different roles in different solid tumors; for example, hsa_circ_0000615 upregulates Sp1 expression by adsorbing miR-150-5p, and thereby promoting the proliferation and metastasis of nasopharyngeal cancer cells." (PMID 34049561, 2021). "In this study, MITA was found to significantly repress the cell viability of both CNE2 and HNE1 cells, indicating Sp1 may be the potential target in the clinical therapy of nasopharyngeal carcinoma." (PMID 25099028, 2014). "Our data revealed that higher level of Sp1 may play important role in the development of nasopharyngeal carcinoma and highlighted the potential use of Sp1 inhibitor in the clinical therapy of NPC." (PMID 25099028, 2014). "Inhibiting the activities of Sp1 or Sp3 can reduce the level of CENP-H, thus affecting the growth of nasopharyngeal carcinoma." (PMID 40071086, 2025). "Sp1-induced AFAP1-AS1 contributes to proliferation and invasion by regulating the miR-497-5p/CELF1 pathway in nasopharyngeal carcinoma." (PMID 35034634, 2022). "As regards to the oncogenic role of sp1, highly expressed circ-ZNF609 sponged miR-150-5p to promote Sp1 expression, hence supporting the proliferation and metastatic abilities of nasopharyngeal carcinoma cells." (PMID 34499009, 2021). "We previously reported that Sp1 activates the transcription of Bmi1 and CENPH in nasopharyngeal carcinoma." (PMID 25099028, 2014). "Only research in nasopharyngeal carcinoma had described that SP1 induced AFAP1-AS1, which could promote nasopharyngeal carcinoma progression by miR-497-5p/CUGBP Elav-like family member 1 (CELF1)." (PMID 37686205, 2023). "In a similar way, millimolar melatonin reduced the migration and metastatic invasion of nasopharyngeal carcinoma cells through the suppression of MMP-9 expression by inhibiting the binding of the transcription factor, specificity protein-1 (SP-1) to DNA at the MMP-9 promoter." (PMID 31684096, 2019). "However, the significance of Sp1 in human head and neck cancers, such as nasopharyngeal carcinoma, has never been explored." (PMID 25099028, 2014). "However, there have been no studies focused on radioresistance of SP1 in nasopharyngeal cancer." (PMID 26922862, 2016).
diabetic nephropathy (16 papers, 2017 to 2025). "SP1 is also implicated in the dysregulation of multiple RNAs in diabetic nephropathy." (PMID 39850832, 2025). "The SP1-mediated upregulation of Prdx6 expression serves as a protective mechanism against podocyte injury in diabetic nephropathy by mitigating oxidative stress and inhibiting ferroptosis." (PMID 39850832, 2025). "Sp1 mediates the upregulation of Prdx6 expression to prevent diabetic nephropathy by alleviating oxidative stress and ferritin deposition, thereby preventing podocyte damage." (PMID 37113991, 2023). "The specificity protein 1 (Sp1)-mediated upregulation of peroxiredoxin 6 (Prdx6) expression in vitro has been found to prevent podocyte injury in diabetic nephropathy by reducing oxidative stress and ferroptosis." (PMID 38076182, 2023). "Empaglifozin improves the diabetic kidney disease by alleviating mitochondrial fission via AMPK/SP1/PGAM5 pathway." (PMID 35456336, 2022). "Here, we examined the behavior of thiamine transporter-1 (THTR1), THTR2, and their transcription factor Sp1 in response to high glucose and altered thiamine availability in renal cells involved in diabetic nephropathy." (PMID 33916491, 2021). "Besides, bioinformatics analysis reveals that SP1 may be related to diabetic nephropathy and WNT/β-catenin pathway." (PMID 39850832, 2025). "Consequently, targeting SP1 may emerge as a viable therapeutic strategy for managing diabetic nephropathy." (PMID 39850832, 2025). "Thus, modulating expression of SP1 may serve as a therapeutic option to treat diabetic nephropathy." (PMID 39850832, 2025). "Furthermore, Jeong has introduced a novel molecular strategy using ring SP1 decoy ODNs delivered via HVJ-liposome gene-delivery technique, showing potential in preventing and treating diabetic nephropathy." (PMID 39850832, 2025). "And transcription factors HIF1α, KLF4, KLF5, RUNX1, SP1, VDR, WT1 may be also related to diabetic nephropathy." (PMID 34735495, 2021). "Transcription factors HIF1α, KLF4, KLF5, RUNX1, SP1, VDR and WT1 may be related to diabetic nephropathy." (PMID 34735495, 2021).
esophageal squamous cell carcinoma (16 papers, 2012 to 2025). Esophageal squamous cell carcinoma (ESCC) is a type of esophageal carcinoma (EC) that can affect any part of the esophagus, but is usually located in the upper or middle third. "Taken together, our findings revealed that miR-145-5p functioned as a tumor suppressor gene by regulating the Sp1/NF-κB signaling pathway in esophageal squamous cell carcinoma." (PMID 28832500, 2017). "Moreover, in esophageal squamous cell carcinoma, overexpression of the epidermal growth factor (EGF) increased specificity of protein 1 (Sp1) phosphorylation and activated the ERK1/2 pathway, thus enhancing FSCN1 expression." (PMID 34830909, 2021).
osteoporosis (16 papers, 2012 to 2025). A condition of reduced bone mass, with decreased cortical thickness and a decrease in the number and size of the trabeculae of cancellous bone (but normal chemical composition), resulting in increased fracture incidence. "Concerning organic matrix, COL1A1 gene is implicated in reduced BMD in osteoporosis; in fact, type I collagen polymorphisms (Sp1 and +1245G/T) play a role in development of osteoporosis and fracture." (PMID 33297501, 2020). "The collagen type I α1 and Sp1 polymorphisms are associated with reduced bone density and osteoporosis." (PMID 25815782, 2015). "In Hungarian patients with primary biliary cirrhosis and high percentage of osteoporosis, there was a lower frequency of s allele Sp1 COLIA1 than in controls." (PMID 23763832, 2013). "In βTM male patients, the presence of the Sp1 mutation is associated with more severe osteoporosis of the spine and the hip compared with female patients." (PMID 22693660, 2012). "For instance, a polymorphism G→T or TT in the regulatory region of COLIA1 at the recognition site for transcription factor Sp1 is associated with the presence of osteoporosis." (PMID 22693660, 2012). "They concluded that men with thalassemia major carrying the Sp1 mutation may develop severe osteoporosis of the spine and the hip more frequently than patients who do not carry this mutation." (PMID 25002928, 2014). "COLIA1 Sp1(G-->T) polymorphism appears to be an important marker for low bone mass and vertebral fracture, raising the possibility that genotyping at this site may be of value in identifying women who are at risk of osteoporosis." (PMID 23731710, 2013). "Previous studies have shown associations between Col1A1 Sp1 polymorphisms and low BMD, osteoporosis, and increased fracture risk, while some have not reached statistical significance." (PMID 30251958, 2019). "In summary, our findings identified that lncRNA SNHG1 regulated by SP1 play a promoting role in osteoporosis development that suppressing osteogenic differentiation and angiogenesis but facilitating osteoclast differentiation by modulating SFRP1-mediated Wnt signaling through sponging miR-181c-5p." (PMID 34732133, 2021). "It is worth to explore whether SP1 can affect the progression of osteoporosis by modulating SNHG1." (PMID 34732133, 2021). "Among Turkish children with forma magna of β-thalassemia and osteoporosis, the s allele of Sp1 COLIA1 was more frequent than in controls (healthy adults without osteoporosis), but the highest BMD-Z score in the lumbar spine was in carriers of s allele (ss>Ss>SS)." (PMID 23763832, 2013). "In addition, male βTM patients who are heterozygous or homozygous at the polymorphic Sp1 site have lower BMD than females and no improvements in spinal osteoporosis in response to treatment with bisphosphonates." (PMID 22693660, 2012).
viral infection (16 papers, 2008 to 2025). "In this section, we outline some of the most commonly affected Sp1 pathways in the presence of viral infection, which are also heavily linked to carcinogenesis." (PMID 40143226, 2025). "Specifically, SMARCB1 inhibition has been shown to impair antiviral responses by disrupting cellular defenses against viral infection, whereas SP1 is known to enhance viral gene transcription, as observed in herpes simplex virus." (PMID 40770872, 2025). "For the purposes of this article, we will only highlight the most-studied PTM, Sp1 phosphorylation in the context of viral infection." (PMID 40143226, 2025). "Transcription factors such as NF-κB or Sp1 that are activated during viral infection are also involved in HERV transactivation for HIV, EBV and HBV." (PMID 39599764, 2024). "The viral infection leads to the downregulation of specificity protein 1 (Sp1), a dominant cis-acting regulatory element of SOD1, which reduces the quantity and activity of SOD1." (PMID 38106478, 2023). "Of note, viral infections also affect miR-22 expression, such as infection by influenza viruses, which modulate miR-22 expression likely through SP1- and c-Myc-dependent transcriptional mechanisms." (PMID 36139435, 2022). "In other work, in viral infection SP1 regulates HIST1H1C which subsequently modulates EHMT1/EHMT2 complex formation and gene expression." (PMID 35139903, 2022). "There are multiple explanations for the enhanced phosphorylation state of Sp1 following viral infection." (PMID 19471608, 2008). "This is in consistent with a previous study defining SP1 could be influenced by virus infection, which is a principal factor for SOD1 transcription." (PMID 26761025, 2016). "Phosphorylation of Sp1 in response to viral infection has been reported in two further studies." (PMID 19471608, 2008). "On one hand, imiquimod boosts IFN-β response and decreases ACE2 expression in HBECs both at baseline and in the presence of the viral infection mimics poly(I:C) and the spike protein of the SARS-CoV-2, SP1." (PMID 34950134, 2021). "Sp1 is known to be activated in response to viral infections, and PKD-dependent Sp1 activation was previously observed in human embryonic kidney cells infected with Kaposi Sarcoma Virus." (PMID 33381112, 2020). "Similarly, SP1 and JUN have been shown to function together to induce TNF expression in response to viral infection and SPI1 has been shown to promote IL10 expression —a cytokine often seen to be dysregulated in autoimmune diseases as in PR3+ AAV." (PMID 36768148, 2023). "Three relevant transcription factors, namely, SP1 (TTRUST database; also identified in the IPA analysis), which has been described as involved in viral transcription, LMO2, a regulator of T-cell translocation, and AP1, are related to viral infection and ROS (Transcription Factor Targets database)." (PMID 38778280, 2024). "Finally, we looked at RIG-I activation by fluorescence microscopy and we observed an enhanced punctuated staining of RIG-I upon Sp1 induction (-DOX: 91±7% vs +DOX: 42,2±11,7%), suggesting the formation of RIG-I aggregates as it was described for MAVS activation in a context of viral infection." (PMID 25738304, 2015).
cholangiocarcinoma (15 papers, 2015 to 2025). A carcinoma that arises from the intrahepatic biliary tree (intrahepatic cholangiocarcinoma) or from the junction, or adjacent to the junction, of the right and left hepatic ducts (hilar cholangiocarcinoma). "In summary, the current study provides novel evidence that KAT2B plays an important tumor suppressive role in cholangiocarcinoma through interaction with SP1 to enhance the expression of NF2 which leads to subsequent inhibition of oncogenic YAP." (PMID 38641672, 2024). "A recent study showed that SP-1 mediates the adhesion of the cell, angiogenic sprouting, transcription factors and vasculogenesis in cholangiocarcinoma cell lines." (PMID 34572295, 2021). "LncRNA SPRY4-IT1 is activated by SP1 and contributes to the malignant progression of cholangiocarcinoma." (PMID 32694944, 2020). "Additionally, Sp1 enhances immunosuppression in cholangiocarcinoma by regulating Snail expression and promoting EMT and immune escape." (PMID 40125551, 2025). "Interestingly, atypical-PKC isoform-mediated phosphorylation of Sp1 positively regulates the Sp1-mediated genes expression in cholangiocarcinoma, which resulted in enhanced invasion and metastasis by influencing growth factor expression and tumor angiogenesis." (PMID 31336725, 2019). "Mechanistically, in cholangiocarcinoma, atypical protein kinase C-iota (aPKC-ι) directly phosphorylates specificity protein 1 (Sp1) to up-regulate P-Sp1 that increased SNAIL expression by promoting Sp1 binding to the SNAIL promoter, resulting in EMT changes and immunosuppression." (PMID 31126310, 2019). "Moderate to high expression of MAT2A and SP1 were present and co-localized in the nuclei in the cancerous tissue from an ESRRG-negative cholangiocarcinoma patient." (PMID 37240447, 2023). "Our in silico analysis revealed that a total of six TFs (SP1, CREB1, MAX, FHL2, RFX1 and HIF1A) were upregulated in cholangiocarcinoma tissues." (PMID 34199886, 2021). "A recent study demonstrated that SP-1-induced MMP remodeling and cell adhesion resulted in vasculogenesis in cholangiocarcinoma." (PMID 34572295, 2021). "For cholangiocarcinoma, TGF-β1 acts as a promoter of tumorigenesis through Sp1-dependent transcriptional activation of vascular endothelial growth factor(VEGF) or Snail activation." (PMID 26441331, 2015). "Sp1 can bind lncRNA sprouty receptor tyrosine kinase signaling antagonist 4–intronic transcript 1 (SPRY4-IT1) promoter and activate its transcription, thereby playing a carcinogenic role in cholangiocarcinoma." (PMID 34145213, 2021). "Moreover, expressions of six TF genes (SP1, CREB1, MAX, FHL2, RFX1, and HIF1A) was positively correlated with the expression of ITGA6 and ITGB1 in cholangiocarcinoma tissues." (PMID 34199886, 2021).